VNN1 (vanin 1)
Diseases named in the same sentence as VNN1 in open-access papers (continued):
Sharing a sentence is not in itself a finding about the gene and the disease.
infection (9 papers, 2011 to 2025). The state of being infected such as from the introduction of a foreign agent such as serum, vaccine, antigenic substance or organism. "Using Vnn1-deficient mice, we have previously showed that pantetheinase activity is required for tissue adaptation to stress induced by damage, infection, or inflammation and more specifically during myofibroblast-dependent tissue repair and fibrosis." (PMID 30456364, 2018). "Consistent with this hypothesis, development of atherosclerotic lesions was increased significantly by infection of apoE−/− mice with lentivirus (LV) encoding mouse VNN1 (LV-VNN1)." (PMID 27281478, 2016). "Case 6 has a sibling with PANS who also developed infection-induced catatonia, who has the TEP1, BTNL9 and VNN1 variants." (PMID 40894167, 2025). "Vanin-1 was identified in one spot and was influenced by coccidia infection, with at least a 2-fold reduction in concentration in response to infection with any of the three species of Eimeria." (PMID 21297942, 2011). "Cysteamine is a simple aminothiol, produced endogenously through the action of pantetheinases such as vanin-1 in the metabolism of co-enzyme A and is a molecule which may have an underappreciated role in immunity to infection." (PMID 34631600, 2021). "The absence of VNN1 could reduce inflammation and oxidative stress during infection or injury." (PMID 36527111, 2022).
metabolic disorders (5 papers, 2016 to 2025). "For the aims of translational medicine, our findings provide a promising approach to treat metabolic diseases caused by dysregulation of Vanin‐1 and lipolysis." (PMID 32714762, 2020). "The fourth domain protein, Vanin-1, which is a unique protein that balances inflammation, metabolic diseases, and oxidative stress, was highly expressed in the control group but showed negligible expression in CML (p <0.0001)." (PMID 35847841, 2022). "A state‐of‐art RNA‐delivery nanosystem is also developed to specifically manipulate in situ Vanin‐1 expression, thus providing a new strategy to treat metabolic disorders." (PMID 32714762, 2020). "Among the significant findings, two gene–amino acid associations are novel (3-methoxytyrosine and DDC, and acisoga and VNN1) and there are two loci, DDC and CPS1, in which mutations are known to cause autosomal recessive metabolic disorders." (PMID 27884205, 2016). "Our present understanding of the vanin-1/PA role in metabolic diseases is ambiguous." (PMID 40954177, 2025).
kidney disease (4 papers, 2019 to 2024). "However, a common finding appears to be the significantly increased concentration of vanin 1 in urine collected in pathophysiological conditions, highlighting vanin 1′s potential as a valuable biomarker for renal diseases." (PMID 31404995, 2019).
bacterial infection (3 papers, 2018 to 2025). "In this article, we shortlisted activated target genes in monocytes during acute bacterial infection, including VNN1, NLRC4, CYP1B1, PFKFB3, LILRA5, NFKBIA or NFKBIZ." (PMID 40581066, 2025). "Upregulation of GJB2, VNN1, DUSP4, SerpinB7, and IL10, and downregulation of PKMYT1, S100A4, GGTA1P, and SLC22A31 were most strongly associated with bacterial infection." (PMID 39395995, 2024).
cardiovascular disease (3 papers, 2007 to 2025). "Altogether, vanin-1 has an atherosclerotic effect, increasing the risk of cardiovascular diseases." (PMID 40954177, 2025). "However, there are some reports on the role of vanin-1 in cardiovascular diseases and cardiovascular disease risk factors." (PMID 40954177, 2025). "The enzyme vanin-1 produces pantothenic acid (PA) and cysteamine, but the role of the vanin-1 /PA axis in metabolic and cardiovascular diseases remains less explored than the vanin-1 /cysteamine pathway." (PMID 40954177, 2025). "More recently, VNN1 has been suggested as a novel gene for cardiovascular disease risk, strongly associated with expression levels of several lipid metabolism/CVD-risk genes, although the underlying pathway of VNN1 and other CVD-risk genes remains unknown." (PMID 18043751, 2007).
vasculopathy (1 paper, 2023). "Pantetheine is also the substrate of vanin-1 which improve vasculopathy in inflammatory conditions by protecting endothelial cells." (PMID 37608823, 2023).
VNN1 also shares sentences with these, for which no sentence is quoted: atherosclerosis (3 papers); type 2 diabetes (3); systemic sclerosis (2); acne (1); Allergy (1); autoimmune thyroid disease (1); bladder cancer (1); cholangiocarcinoma (1); chronic kidney disease (1); glioma (1); Glucose intolerance (1); graft versus host disease (1); Granuloma (1); hematologic malignancies (1); IgA nephropathy (1); IgA Vasculitis (1); infectious disease (1); inflammation (1); intrauterine growth retardation (1); liver dysfunction (1); lymphoma (1); malignant brain tumors (1); nephritis (1); non-alcoholic fatty liver disease (1); peripheral artery disease (1); psoriasis (1); rectal adenocarcinoma (1); thyroid tumor (1); tuberculosis (1); Ureteral obstruction (1).